VTRNA1-3 (vault RNA 1-3)
Synonyms: hvg-3; HVG3; VR3; VAULTRC3
Gene: Gene (Ensembl biotype vault_RNA) on chromosome 5 (140,726,158 to 140,726,246, forward strand). Ensembl gene ENSG00000202515.
Homologues: Orthologues: chimpanzee Vault (94% identical), macaque Vault (92% identical), guinea pig Vault (75% identical), pig Vault (75% identical), guinea pig Vault (73% identical), rabbit Vault (71% identical), rabbit Vault (69% identical). Paralogues in human: VTRNA1-2 (87% identical), VTRNA1-1 (80% identical), VTRNA3-1P (72% identical), Vault (63% identical), Vault (58% identical), VTRNA2-2P (55% identical), Vault (53% identical).
Diseases named in the same sentence as VTRNA1-3 in open-access papers:
VTRNA1-3 is named in the same sentence as 5 diseases in open-access papers, as found by Europe PMC text mining. Sharing a sentence is not in itself a finding about the gene and the disease. The quoted sentences say what the papers report.
myelodysplastic syndrome (1 paper, 2021). A clonal hematopoietic disorder characterized by dysplasia and ineffective hematopoiesis in one or more of the hematopoietic cell lines. "In addition, a potential TSG role has been put forward for vtRNA1-3 in Myelodysplastic syndrome (MDS) (Helboet al., 2015)." (PMID 34354812, 2021).
VTRNA1-3 also shares sentences with these, for which no sentence is quoted: infection (2 papers); cancer (1); lung carcinoma (1); varicocele (1).